KIF4A (kinesin family member 4A)
Diseases named in the same sentence as KIF4A in open-access papers (continued):
Sharing a sentence is not in itself a finding about the gene and the disease.
brain cancer (1 paper, 2022). A primary or metastatic malignant neoplasm affecting the brain. "Our tissue assay results showed that KIF4A expression was upregulated in advanced grade WHO III/IV compared with grade WHO I/II in brain cancer tissues." (PMID 36606197, 2022). "KIF4A expression was then examined in an expanded brain cancer cohort by a tissue microarray (TMA)." (PMID 36606197, 2022).
endometriosis (1 paper, 2025). The growth of functional endometrial tissue in anatomic sites outside the uterine body. "Our study has identified eight potential mitosis hub genes (KIF4A, BUB1B, NEK2, FBXO5, KIF11, CENPE, CCNA2, and NCAPG) that exhibit excellent diagnostic properties for endometriosis." (PMID 40772274, 2025). "Then, we identified 11 potential mitosis-related downregulated hub genes, among which eight genes (KIF4A, BUB1B, NEK2, FBXO5, KIF11, CENPE, CCNA2, and NCAPG) showed good diagnostic properties of endometriosis and two genes (CCNA2, CENPE) were closely related to infertile endometriosis." (PMID 40772274, 2025). "We used the GSE25628 dataset to detect the expression of selected target genes, and the results showed that the differential expression of eight MRHGs (KIF4A, BUB1B, NEK2, FBXO5, KIF11, CENPE, CCNA2, and NCAPG) between control and endometriosis patients was consistent with predictions." (PMID 40772274, 2025).
Ewing sarcoma (1 paper, 2025). A small round cell tumor that lacks morphologic, immunohistochemical, and electron microscopic evidence of neuroectodermal differentiation. "Additionally, the aberrant expression and function of KIF4A have been implicated in the pathogenesis and progression of a variety of solid tumours, including insulinoma, pleural mesothelioma (PM), meningioma, skin cutaneous melanoma (SKCM), and Ewing sarcoma (ES)." (PMID 41361459, 2025).
liver cirrhosis (1 paper, 2025). "In HCC, a four-gene combination involving KIF4A, UBE2T, CDCA3, and CDCA5 can track disease progression from chronic active hepatitis B (CAH-B) and liver cirrhosis (LC) to HCC." (PMID 41361459, 2025).
melanoma (1 paper, 2022). A malignant, usually aggressive tumor composed of atypical, neoplastic melanocytes. "Receiver operating characteristic (ROC) curves showed an area under the curve (AUC) >90.0% for KPNA2, DTL, BACE2, DTYMK, E2F3 and SLC25A13, >80.0% for CCNA2, FOXM1, KIF4A, SLC45A2, COPS8, SLC45A13 and 70.0% for CDC25A and LINC00520; all significantly discriminating melanoma from benign nevi." (PMID 36320118, 2022).
meningioma (1 paper, 2019). A generally slow growing tumor attached to the dura mater. "Accordingly, KIF4A could still serve as a target in meningiomas and deserves further investigation." (PMID 30991738, 2019). "Regarding KIF4A and KIF11, we made similar observations, though the number of meningiomas with more than 50% kinesin-expressing cells further increased in WHO°II and °III tumors." (PMID 30991738, 2019). "To finally address the question, if differentially expressed kinesin family members have an impact on tumor cell proliferation of meningioma cells, we performed a siRNA-mediated knockdown of KIFC1, KIF4A, KIF11, KIF14 and KIF20A." (PMID 30991738, 2019). "Therefore, we re-analyzed our previous microarray dataset of benign, atypical, and anaplastic meningiomas (n = 62) and got evidence for differential expression of five kinesins (KIFC1, KIF4A, KIF11, KIF14 and KIF20A)." (PMID 30991738, 2019). "Therefore, we used ten meningioma tissue samples for each WHO grade and stained them for KIFC1, KIF4A, KIF11, KIF14 and KIF20A." (PMID 30991738, 2019). "To query if kinesin family members might represent novel molecular therapeutic targets, we re-analyzed our previous microarray data set of benign, atypical and anaplastic meningiomas and identified five differentially expressed kinesins (KIFC1, KIF4A, KIF11, KIF14 and KIF20A)." (PMID 30991738, 2019). "KIF4A showed a differential protein and mRNA expression and discrimination of non-recurrent WHO°II meningiomas vs. clinically aggressive tumors of the same grade." (PMID 30991738, 2019).
Obesity (1 paper, 2022). Accumulation of substantial excess body fat. "Several hub genes, such as TOP2A, CENPF, TYMS, AURKA, KIF4A, and KIF20A, are related to the cell cycle and DNA replication, implicating the close relationship between obesity and cancer." (PMID 36232337, 2022).
ovarian failure (1 paper, 2009). "Therefore an eventual functional alteration of KIF4A could be associated with an altered division and the depletion of germ cells during embryogenesis; ovarian failure might be caused by the precocious loss of oogones and subsequent gonadal deficiency." (PMID 19781104, 2009).
renal cell carcinoma (1 paper, 2019). "KIF4A were identified as prognostic gene or key gene involved in the metastasis of renal cell carcinoma in recent survey." (PMID 32063918, 2019).
stomach adenocarcinoma (1 paper, 2025). "In stomach adenocarcinoma (STAD), KIF4A is closely linked to the homologous recombination repair (HRR) pathway and is co-upregulated with core HRR genes like RAD5142." (PMID 41361459, 2025). "In stomach adenocarcinoma (STAD), KIF4A is co-upregulated with HRR genes like RAD51, exacerbating genomic instability." (PMID 41361459, 2025).
triple-negative breast carcinoma (1 paper, 2025). An invasive breast carcinoma which is negative for expression of estrogen receptor (ER), progesterone receptor (PR), and human epidermal growth factor receptor 2 (HER2). "In triple-negative breast cancer, high KIF4A expression is linked to increased sensitivity to PLK1 inhibitors, such as GSK461364138." (PMID 41361459, 2025).
X-linked intellectual disability (1 paper, 2019). An X-linked intellectual deficiency in which not enough information is known, reported or published to indicate whether a gene causes non-syndromic or syndromic presentations. "Variants in KIF4A are reported to cause X-linked intellectual disability (OMIM: 300923)." (PMID 30679815, 2019).
tumor (65 papers, 2013 to 2026). "In colorectal cancer (CRC), elevated KIF4A expression is positively associated with poor tumour regression following neoadjuvant chemoradiotherapy (nCRT)." (PMID 41361459, 2025). "Multiple studies found that high KIF4A expression at both the protein and RNA levels was associated with poor prognosis and tumour stage in LUAD." (PMID 40002279, 2025). "Patients with high KIF4A expression were often linked to poor clinical outcomes, including worse OS, higher risk of recurrence and metastasis, increased tumor size, advanced T stage, as well as terrible nodule status." (PMID 38433242, 2024). "We found that high KIF4A expression was significantly associated with tumor size >3 cm (p = 0.048) and advanced tumor grade (p = 0.048) and tumor stage (p < 0.001)." (PMID 37039264, 2023). "The loss of KIF4A leads to tumor formation, and aneuploidy can act as a primary trigger of tumorigenesis." (PMID 30872592, 2019). "To provide insight into the molecular mechanism underlying the G0/G1 phase cell cycle-related effect of KIF4A, we focused on the universal cell cycle inhibitor p21, a tumor suppressor involved in the regulation of G0/G1 phase arrest and cell proliferation." (PMID 29706624, 2018). "Mechanistically, KIF4A levels are associated with the infiltration of activated memory T cells and mast cells in the tumour microenvironment, suggesting its potential role in influencing tumour progression through the modulation of immune cell infiltration and tolerance." (PMID 41361459, 2025). "Further analysis revealed that the risk genes IQGAP3, KRTAP5-1, and KIF4A affected the expression of genes in relation to ICIs in tumor tissues, which may affect the treatment response to ICIs." (PMID 37370891, 2023). "In the present study, KIF4A expression in different subtypes of the prostate was also significantly different from normal samples, and KIF4A expression was also found to be associated with tumor-infiltrating immune cells." (PMID 34996995, 2022). "Moreover, our follow-up analysis exhibited that upregulation of KIF4A expression was positively linked to increased invasion depth, tumor diameter, lymph node metastasis and advanced TNM stage." (PMID 34775374, 2021). "Given that the expression of KIF4A was associated with tumor diameter, we wondered whether KIF4A facilitated the proliferation of CRC cells." (PMID 29706624, 2018). "Based on these findings, the aneuploidy associated with aberrant mitosis after Kif4A depletion can promote tumor formation, but it remains unclear whether this is a direct consequence of its role in chromosome congression." (PMID 28218637, 2017). "Moreover, further multivariate Cox analysis showed that KIF4A, FIGO stage, and tumor residual were independently associated with OS, which may imply that KIF4A may be an independent prognostic predictor for EC patients." (PMID 35126794, 2022). "Mechanistically, KIF4A likely drives ccRCC progression through two main pathways: regulating the cell cycle and remodelling the tumour immune microenvironment, establishing it as a potential prognostic biomarker associated with immune infiltration." (PMID 41361459, 2025). "In oral squamous cell carcinoma (OSCC), KIF4A is significantly upregulated in both cells and tissues, correlating with tumour size." (PMID 41361459, 2025). "In bladder cancer (BC), KIF4A contributes to disease progression by modulating the tumour immune microenvironment." (PMID 41361459, 2025). "Beyond cancer, accumulating genetic and functional studies demonstrate that KIF4A also plays indispensable roles in non-neoplastic diseases, highlighting its broader biological relevance." (PMID 41361459, 2025). "KIF4A thus serves as a key regulator of OSCC tumour progression and represents a potential therapeutic target." (PMID 41361459, 2025).
tumor (continued). "This review systematically outlines the biological characteristics of KIF4A, summarizes its central roles in neoplastic diseases as an oncogene, and explores its involvement in neurodevelopmental disorders." (PMID 41361459, 2025). "Functional studies indicate that KIF4A knockdown triggers DNA damage response, cell cycle arrest, and apoptosis, significantly curtailing tumour proliferation." (PMID 41361459, 2025). "In summary, these studies collectively establish a clear link between tumor progression and three kinesin genes (KIF4A, KIF20A, and KIF11)." (PMID 41462522, 2025). "Mechanistically, KIF4A promotes the reorganization of the actin cytoskeleton by transcriptionally repressing Rac1 and Cdc42, thereby enhancing tumour cell proliferation, invasion, and migration." (PMID 41361459, 2025). "Future studies should focus on elucidating the mechanisms behind KIF4A’s functional switching in various microenvironments and accelerating the development of highly selective tumour delivery systems to enhance treatment safety." (PMID 41361459, 2025). "Meanwhile, according to the IHC staining results of 136 paired tumor pathological sections, it was also demonstrated that high KIF4A expression was positively correlated with poor OS and DFS of HCC patients." (PMID 38433242, 2024). "Consistently, in 16 UBC patients at our hospital, KIF4A protein was generally highly expressed in tumor tissue but barely detectable in paired normal bladder tissue." (PMID 37039264, 2023). "High expression of KIF4A in OS predicted poor prognosis and promoted tumor growth by activating the MAPK pathway." (PMID 36849972, 2023). "Immunocytochemistry showed KIF13A and KIF26A mainly localized in cytoplasm and membrane, and KIF13B and KIF4A mainly concentrated at membrane and nuclear that significantly upregulated in tumor samples." (PMID 36837615, 2023). "The current research focused on the role of IQGAP3 and KIF4A in the tumor development process; nonetheless, how these molecules affect the response to ICI treatment at the molecular level must be elucidated at a later stage." (PMID 37370891, 2023). "We also measured the expression level of kinesin family member 4 (KIF4A) in tumor tissues, which also plays a role in chromosome disjunction during mitosis, and found that KIF4A was highly expressed in tumor tissues with high ERCC6L expression levels." (PMID 37667329, 2023). "The associations of ATAD2 and KIF4A with ESCC patient clinical outcome were analyzed, including age, gender, tumor size, tumor differentiation, and distant lymph node metastasis." (PMID 36046597, 2022). "Kif4A expressions in tumor tissues were detected by IHC and quantified by calculating the IOD of each stained area (IOD/area)." (PMID 35882623, 2022). "The representative images showed that knockdown of KIF4A resulted in smaller tumor size in the excised mice brain tissue." (PMID 36606197, 2022). "We further explored its function, finding that knockdown of KIF4A distinctly suppressed the proliferation of BC cells, suggesting that it acted as a tumor promotor in BC progression." (PMID 35646102, 2022). "It was found that Kif4A expression in tumor tissues of group PR was significantly lower than those in groups SD and PD." (PMID 35882623, 2022). "Here, we find that Kif4A expression in pretreated tumor tissue is positively correlated with poorer tumor regression after receiving nCRT (P=0.005)." (PMID 35882623, 2022). "Subsequently, we used ESTIMATE and ssGSEA algorithms to excavate the correlation between KIF4A, tumour-infiltrating immune cells, and related gene markers of immune cells." (PMID 35126794, 2022). "A series of assays in vitro and in vivo revealed that KIF4A down-regulation inhibited tumor growth and reduced cell migration and invasion." (PMID 36606197, 2022). "The knockdown of KIF4A in nude mice promotes malignant transformation from normal cell and tumor formation." (PMID 36606197, 2022).
tumor (continued). "We collected tumor samples 21 days after addition of doxycycline and observed that KIF4A repression remained stable at this time point." (PMID 34326322, 2021). "The results indicated that KIF4A protein expression levels were markedly correlated with tumor diameter (P = 0.021), degree of infiltration (P = 0.012), lymph node metastasis (P = 0.047), distant metastasis (P = 0.009) and TNM stage (P < 0.001)." (PMID 34775374, 2021). "In the present study, we clarified that expression of FANCB, KIF15, KIF4A, ERCC6L, and UBE2C are regulated by DNA methylation changes of their promoter CpGis and closely associated with tumor prognosis in HCC using the TCGA database." (PMID 32703154, 2020). "KIF4A expression was correlated with tumor size in KIF4A-positive cases, suggesting that SAC activation plays a significant role in cellular proliferation in OSCC." (PMID 31019584, 2019). "ROC curve indicated that CCNB2, FBXO5, KIF4A, MCM10, and TPX2 exhibited excellent diagnostic efficiency for normal and tumor tissues." (PMID 30254986, 2018). "The results showed that the tumors in the group injected with HCT116 cells with stable KIF4A knockdown exhibited significantly lesser tumor growth capacity and smaller tumor volumes than the control group." (PMID 29706624, 2018). "High KIF4A protein expression was significant positively correlated with tumor diameter (P < 0.001), depth of invasion (P < 0.001), TNM: Tumor, Node, Metastases stage (P < 0.001), lymph node metastasis (P < 0.001), and distant metastasis (P = 0.034)." (PMID 29706624, 2018). "Taken together, these data indicated that KIF4A expression was increased in HCC tumour tissues and cells." (PMID 29396392, 2018). "Results indicated that KIF4A protein expression levels were markedly correlated with encapsulation (P = 0.036), tumour size (P = 0.004), and survival (P = 0.0003)." (PMID 29396392, 2018). "We then used in vitro HCC cell models to address the molecular mechanism by which KIF4A promotes hepatic malignant transformation and tumour progression." (PMID 29396392, 2018). "The proportion of relative larger tumor (dimension of primary tumor >5 cm) reached 62% (21/34) in KIF4A-high group while only 30% in KIF4A-low group." (PMID 28646197, 2017). "Owing to above observations, we postulate that there would be a possible link between aberrant change of Kif4A and induction of recruited macrophages which contribute to the generation of immunotolerant tumor microenvironment." (PMID 28533507, 2017). "As the same with our observation in co-culture system, the expression of Kif4A in OSCC tumor cells was at a high level and tumor-infiltrating macrophages express Kif4A at a middle level (as shown in the black arrow)." (PMID 28533507, 2017). "The expression level of KIF4A in tumor tissue is significantly associated with the survival time, and a significant correlation between KIF4A expression and clinical information stage, metastasis and tumor dimension was observed." (PMID 28646197, 2017). "Western blot assays showed that the protein level of KIF4A was also higher in HCC tumor tissues than in their matched counterparts." (PMID 28646197, 2017). "Prediction models based on KIF4A expression can reliably predict tumour cell sensitivity to platinum-based agents, taxanes, and topoisomerase inhibitors, achieving an area under the curve (AUC) exceeding 0.85, thus providing a valuable tool for personalized chemotherapy regimens." (PMID 41361459, 2025). "By upregulating CXCL5 expression, KIF4A recruits MDSCs which dampens anti-tumour immunity." (PMID 41361459, 2025).